PDGFA (platelet derived growth factor subunit A)
Description:
Growth factor that plays an essential role in the regulation of embryonic development, cell proliferation, cell migration, survival and chemotaxis. Potent mitogen for cells of mesenchymal origin. Required for normal lung alveolar septum formation during embryogenesis, normal development of the gastrointestinal tract, normal development of Leydig cells and spermatogenesis. Required for normal oligodendrocyte development and normal myelination in the spinal cord and cerebellum. Plays an important role in wound healing. Signaling is modulated by the formation of heterodimers with PDGFB (By similarity).
Synonyms: PDGF1; PDGF-A
Tractability: Small molecule: it has a high-quality binding pocket. Antibody: its Gene Ontology location is reachable by antibodies, with high confidence; UniProt places it where antibodies can reach, with medium confidence; UniProt predicts a signal peptide or a membrane-spanning region. PROTAC: a small molecule that binds it is known.
Target class: Secreted protein
Gene: Protein-coding gene on chromosome 7 (497,258 to 520,695, reverse strand). Ensembl gene ENSG00000197461.
Subcellular location: Secreted
Subcellular location (Human Protein Atlas): Golgi apparatus; Predicted to be secreted
Pathways (Reactome):
Signal Transduction: Downstream signal transduction; PI5P, PP2A and IER3 Regulate PI3K/AKT Signaling; PIP3 activates AKT signaling; RAF/MAP kinase cascade; Signaling by PDGF
Cellular responses to stimuli: NFE2L2 regulating tumorigenic genes
Disease: Constitutive Signaling by Aberrant PI3K in Cancer
Extracellular matrix organization: Non-integrin membrane-ECM interactions
Hemostasis: Platelet degranulation
Gene Ontology:
Molecular function: collagen binding; growth factor activity; platelet-derived growth factor binding; platelet-derived growth factor receptor binding; protein binding; protein heterodimerization activity; protein homodimerization activity; receptor ligand activity
Biological process: negative chemotaxis; negative regulation of phosphatidylinositol biosynthetic process; negative regulation of platelet activation; platelet-derived growth factor receptor signaling pathway; positive regulation of cell migration; positive regulation of cell population proliferation; positive regulation of ERK1 and ERK2 cascade; positive regulation of fibroblast proliferation; positive regulation of MAPK cascade; positive regulation of metanephric mesenchymal cell migration by platelet-derived growth factor receptor-beta signaling pathway; positive regulation of phosphatidylinositol 3-kinase/protein kinase B signal transduction; regulation of DNA biosynthetic process; regulation of glomerular mesangial cell proliferation; regulation of smooth muscle cell migration; response to wounding; actin cytoskeleton organization; angiogenesis; animal organ morphogenesis; cell activation; cell projection assembly; cell-cell signaling; embryonic lung development; hair follicle development; lung alveolus development; peptidyl-tyrosine autophosphorylation; and 7 more
Cellular component: cell surface; extracellular region; platelet-derived growth factor complex; platelet-derived growth factor receptor-ligand complex; endoplasmic reticulum lumen; Golgi lumen; Golgi membrane; microvillus; platelet alpha granule lumen; membrane
Genetic constraint (gnomAD): Loss-of-function variants: 2 observed, 17.28 expected, observed/expected ratio (o/e) 0.12, 90% interval 0.046 to 0.36. The upper end of that interval is the gene's LOEUF score, 0.36, which puts it in group 1 of 6, group 1 being the genes least tolerant of losing a copy. Missense variants: 190 observed, 219.72 expected, observed/expected ratio (o/e) 0.86, 90% interval 0.77 to 0.98. Synonymous variants: 112 observed, 90.26 expected, observed/expected ratio (o/e) 1.24, 90% interval 1.06 to 1.45.
Homologues: Orthologues: macaque PDGFA (94% identical), mouse Pdgfa (92% identical), dog PDGFA (88% identical), pig PDGFA (87% identical), rat Pdgfa (85% identical), guinea pig PDGFA (83% identical), chimpanzee PDGFA (73% identical), tropical clawed frog pdgfa (71% identical), zebrafish PDGFA (58% identical), zebrafish pdgfaa (58% identical), rabbit PDGFA (57% identical), zebrafish pdgfab (56% identical), and 2 more. Paralogues in human: PDGFB (41% identical).
Diseases named in the same sentence as PDGFA in open-access papers:
PDGFA is named in the same sentence as 155 diseases in open-access papers, as found by Europe PMC text mining. Sharing a sentence is not in itself a finding about the gene and the disease. The quoted sentences say what the papers report.
glioma (50 papers, 2004 to 2024). A benign or malignant brain and spinal cord tumor that arises from glial cells (astrocytes, oligodendrocytes, ependymal cells). "Given the association of PDGFRα with IDH-mutant glioma, the use of PDGFA as an oncogenic driver seems more relevant because PDGFA activates only PDGFRα." (PMID 30416682, 2018). "In conclusion, here we show that PDGFA is expressed in different types of gliomas and its absence is associated with a poor prognosis." (PMID 19707201, 2009). "We next examined whether PDGFA expression was associated with the histopathology of glioma and patient prognosis." (PMID 31300060, 2019). "Histologically, in GFAP-Cre PDGFA transgenic mice, spontaneous gliomas exhibited characteristics of both astrocytes and oligodendrocytes and were classified as WHO grade III oligoastrocytomas." (PMID 38473403, 2024). "Another study using the RCAS/TVA system demonstrated that glioma-genesis in the context of mutant IDH1 with shp53 and/or Cdkn2a loss, was only facilitated when combined with PDGFa." (PMID 38012788, 2023). "PDGFA, the core gene with increased expression on chromosome 7, widely exists in glioblastomas and has been demonstrated to be crucial in glioma." (PMID 37691922, 2023). "In an experimental model, PDGFA enhanced the growth of IDH1R132H mutant immortal Cdkn2a, Atrx, and Pten deficient astrocytes and PDGFA cooperated with IDH1R132H and loss of Cdkn2a, Atrx, and Pten to promote glioma formation in vivo." (PMID 38012788, 2023). "It has been known that EFNA1 is a major cognate ligand of EPHA2 in vivo, but the function of EFNA1 is thought to impair EPHA2 activity in glioma cells, which promoted us to investigate the difference of PDGFA/EPHA2 axis and EFNA1/EPHA2 axis." (PMID 35105853, 2022). "It should be mentioned that PDGFA was a prognostic marker for glioma and analyses on several glioma databases consistently indicated that high expression of PDGFA predicted poor survival." (PMID 34987659, 2022). "Of these, only one gene (PDGFA) was a member of the known pathways involved in glioma disease development, according to DAVID." (PMID 35877430, 2022). "CEBPD also regulates the stemness of glioma cells by activating platelet-derived growth factor subunit A (PDGFA) expression due to inflammatory stimulation." (PMID 36153549, 2022). "We then examined the expression levels of RELAFUS1 target genes in RNA-seq data of normal mouse brains, PDGFA-driven gliomas, and RELAFUS1-driven ependymomas." (PMID 33685520, 2021). "We observed that many RELAFUS1 target genes were significantly up-regulated in RELAFUS1-driven ependymomas compared to both normal brains and PDGFA-driven gliomas." (PMID 33685520, 2021). "We observed that a significant portion of these genes was commonly up- or down-regulated in RELAFUS1-driven mouse ependymomas compared to normal brains or PDGFA-driven gliomas, indicating the creation of a RELAFUS1-specific transcriptional network." (PMID 33685520, 2021). "The cytolytic activity-related PDGFA and EGFR genes have been found to be overexpressed in glioma, and a positive association between cytolytic activity and HLA expression has been observed; however, the underlying mechanisms are still being evaluated." (PMID 34660294, 2021). "In tumor cells, PDGFRA and PDGFA are commonly found and PDGFB and PDGFRB are expressed in glioma-linked endothelial cells." (PMID 34199460, 2021). "Further, as bolstered by the overlapping of H3K27ac peaks with the RELAFUS1 peaks in the 2700081O15Rik gene, 2700081O15Rik was remarkably up-regulated in RELAFUS1-driven ependymomas relative to normal brains and PDGFA-driven gliomas." (PMID 33685520, 2021). "PDGFA was expressed on glioma, lung cancer, colorectal cancer, head and neck cancer, stomach cancer, liver cancer, pancreatic cancer, renal cancer, urothelial cancer, cervical cancer, endometrial cancer, and melanoma." (PMID 32434423, 2020).
glioma (continued). "Taken together, these data suggest that the expression of PDGFA is increased in glioma and is correlated with CEBPD expression." (PMID 31300060, 2019). "Herein, we provide evidences showing the upregulation of PDGFA expression and promotion of glioma stemness by CEBPD under inflammatory stimulation." (PMID 31300060, 2019). "We also found that the expression level of PDGFA significantly correlated with the expression level of CEBPD in these glioma samples." (PMID 31300060, 2019). "Previous studies indicate that PDGFA can promote glioma proliferation, invasion, and self-renewal, thus suggesting that PDGFA regulates GSC stemness and promotes glioma progression." (PMID 31300060, 2019). "We show that CEBPD is responsive to IL-1β stimulation and enhances the transcription and expression of PDGFA, which, in turn, promotes glioma stemness." (PMID 31300060, 2019). "Further analysis of the genomic database and tissue array revealed that the expression levels between CEBPD and PDGFA were coincident in glioma patient samples." (PMID 31300060, 2019). "Similar to the PDGFA alone-induced lesions, the initial tumors (day 30–40) with the PDGFA/shp53 combination showed MRI/S characteristics consistent with low-grade glial neoplasms." (PMID 28358926, 2017). "To investigate the functional relationship between PDGFRα and GOLM1, we examined GOLM1 protein levels in parental and modified glioma cells treated with PDGFA." (PMID 29282077, 2017). "The PDGFA only vector infection yielded neoplasia consistent with low-grade glioma approximately 250 days following injection, similar to that observed in Ntv-a mice." (PMID 28358926, 2017). "PDGFA/PDGFRα-regulated GOLM1 promotes glioma progression possibly through activation of a key signaling kinase, AKT." (PMID 29282077, 2017). "A recent study showed that the long isoform of PDGFA overexpressed in the brain abnormalities and glioma-Like lesions in astrocytic cells in mice, and induced accumulation of immature cells in the mouse brain." (PMID 24622401, 2014). "The elevated expression of WISP1 (CCN4) and PDGFA proteins in the invasive glioma cells was confirmed." (PMID 25365423, 2014). "In “secondary glioma pathway”, gains of PDGFA (1 in LGG and 2 in HGG), PDGFRA (2 in LGG and 2 in HGG) and CDK4 (1 in LGG and 2 in HGG) and RB1 (2 in HGG), and losses of RB1 (1 in LGG and 2 in HGG) are also identified." (PMID 23451178, 2013). "PDGFRA and PDGFA have been shown to be expressed in tumour cells, whereas PDGFB and PDGFRB have been found in glioma-associated endothelial cells." (PMID 19707201, 2009). "It should be noted, however, that there is a paucity of data on prevalence of PDGFA protein expression in primary glioma specimens." (PMID 19707201, 2009). "CEBPD can also maintain the stemness of glioma stem cells by promoting PDGFA expression." (PMID 32997416, 2020). "Among them, PDGFA is found in 70% of gliomas and is highly expressed in GBM." (PMID 31300060, 2019). "PDGFA signaling maintains glioma stem cell growth and self-renewal." (PMID 31300060, 2019). "Moreover, those gliomas exhibited significantly increased copy number alterations including recurrent focal amplifications of PDGFA and EGFR, as well as recurrent deletions of CDKN2A/B." (PMID 31428092, 2019). "Moreover, EGR1 correlated with stemness markers and proliferation by orchestrating a PDGFA-dependent growth-stimulatory loop in primary glioma stem-like cells." (PMID 29246166, 2017). "Overall, PDGFA was highly expressed in all histological types of gliomas." (PMID 19707201, 2009).
glioma (continued). "Previous studies on PDGFA mRNA expression reported high levels of PDGFA in gliomas." (PMID 19707201, 2009). "In this study, we intended to analyse the expression of PDGFA and its receptor PDGFRA, as well as the underlying genetic (mutations and amplification) mechanisms driving their expression in a large series of human gliomas." (PMID 19707201, 2009). "However, the role of PDGFA in glioma in the inflammatory environment remains to be elucidated." (PMID 31300060, 2019). "Thus, the aim of this study was to define the frequency of PDGFRA and PDGFA expression in a large series of gliomas and to determine whether expression of PDGFRA is driven by PDGFRA gene mutations and/ or amplification." (PMID 19707201, 2009). "Interestingly, we found that the absence of PDGFA expression is significantly associated with age and poor prognosis in patients with glioma." (PMID 19707201, 2009). "However, the absence of PDGFA expression was significantly associated (P=0.023) with age (>45 years) and with a poor prognosis in glioma patients (P=0.026)." (PMID 19707201, 2009). "While these four genes (PDGFA, PDGFRA, CREB1, and PLAT) have been studied individually, our findings highlight their collective significance in glioma." (PMID 39606019, 2024). "The discovery of this quadruple (PDGFA–PDGFRA–CREB1–PLAT), capable of distinguishing between grade III and grade IV gliomas, holds substantial implications for patients affected by these tumors." (PMID 39606019, 2024). "PDGFA/PDGFRA signaling has been shown to induce EMT through stimulation of ZEB1, thereby promoting glioma tumor growth and invasion and GSCS stemness." (PMID 36829235, 2023). "A recent comparative RNA-seq analysis identified that many genes are commonly upregulated in both gliomas (eg., IDH wild-type) and BrMs, including the angiogenic factor VEGFA, growth factors PDGFA, TGFB1, SPP1, and the protease inhibitor TIMP-116." (PMID 36216799, 2022). "In animal model studies, PDGFA activates the PDGFRA-positive neural stem cell proliferation in the subventricular zone, which differentiates and develops lesions similar to glioma." (PMID 34199460, 2021). "We further demonstrate that PDGFA is responsive to CEBPD induction in glioma spheroid cells, and CEBPD regulates PDGFA transcription by binding to the PDGFA promoter region." (PMID 31300060, 2019). "In this study, we have demonstrated that IL-1β-induced CEBPD promotes glioma stemness in U373MG, T98G, and PT#3-spheroid cells by elevating PDGFA expression." (PMID 31300060, 2019). "The glioma tissue microarrays were used for CEBPD and PDGFA expression by immunohistochemistry staining." (PMID 31300060, 2019). "We found that the expression of PDGFA was significantly higher in glioma samples and was correlated with the CEBPD expression levels in these glioma samples." (PMID 31300060, 2019). "The last finding of this research belongs to the regulation of PDGFA/PDGFRα on GOLM1, while GOLM1 was also a key element of PDGFA/PDGFRα-mediated activation of AKT, as well as the progression of glioma cells." (PMID 29282077, 2017). "The RTK ligands including EFNB2, SEMA3D, PDGFA, SEMA3A and FGF14 were amplified in ~5% of the RMPAhigh gliomas." (PMID 27385209, 2016). "Expression of the long form of PDGFA was originally identified in tumor cells, and PDGFAA was cloned from a human glioma cell line." (PMID 24622401, 2014). "Given the retrospective nature of our study, further analysis of the prognostic impact of PDGFA and PDGFRA expression in gliomas is warranted." (PMID 19707201, 2009). "The concurrent expression of PDGFA and PDGFRA in different subtypes of gliomas, reinforce the recognised significance of this signalling pathway in gliomas." (PMID 19707201, 2009). "PDGFA and PDGFRA expression was evaluated by immunohistochemistry in a series of 160 gliomas of distinct World Health Organization (WHO) malignancy grade." (PMID 19707201, 2009).
glioma (continued). "PDGFA and PDGFRA expression was found in 81.2% (130 out of 160) and 29.6% (48 out of 160) of gliomas, respectively." (PMID 19707201, 2009). "Interestingly, we observed a significantly lower expression of genes such as PDGFA, FGFR1, DLL4, and VEGFA in glioma patients with a higher TMIGD2 profile." (PMID 37261362, 2023). "Furthermore, we examined the protein expression of PDGFA and CEBPD in tissue arrays of human glioma samples by immunohistochemical analyses." (PMID 31300060, 2019). "Furthermore, we demonstrated that PDGFA/ PDGFRα upregulates GOLM1, and that GOLM1 acts as a key component in PDGFA/ PDGFRα-mediated glioma progression." (PMID 29282077, 2017). "Pathway enrichment analysis identified four essential genes—PDGFA (ligand), PDGFRA (receptor), CREB1 (TF), and PLAT (target gene)—involved in the Receptor Tyrosine Kinases (RTK) signaling pathway, which plays a pivotal role in glioma progression from grade III to grade IV." (PMID 39606019, 2024). "Moreover, in KEGG pathways, top-ranked eight PDGFA-involved categories according to P-Value were EGFR tyrosine kinase inhibitor resistance, Ras signaling pathway, Pathways in cancer, Glioma, MicroRNAs in cancer, Rap1 signaling pathway, focal adhesion, and PI3K-AKT signaling pathway." (PMID 35105853, 2022). "Consistently, glioma samples expressed higher PDGFA than non-tumor brain tissue." (PMID 31300060, 2019). "Based on the concurrent expression of PDGFA and PDGFRA in glioblastomas, it could be hypothesised that autocrine/paracrine loops may be present in these tumours, corroborating the importance of this signalling pathway in gliomas." (PMID 19707201, 2009).